TMEM100 (transmembrane protein 100)
Description:
Plays a role during embryonic arterial endothelium differentiation and vascular morphogenesis through the ACVRL1 receptor-dependent signaling pathway upon stimulation by bone morphogenetic proteins, such as GDF2/BMP9 and BMP10. Involved in the regulation of nociception, acting as a modulator of the interaction between TRPA1 and TRPV1, two molecular sensors and mediators of pain signals in dorsal root ganglia (DRG) neurons. Mechanistically, it weakens their interaction, thereby releasing the inhibition of TRPA1 by TRPV1 and increasing the single-channel open probability of the TRPA1-TRPV1 complex.
Synonyms: FLJ10970; FLJ37856
Tractability: Antibody: its Gene Ontology location is reachable by antibodies, with high confidence; UniProt places it where antibodies can reach, with medium confidence; UniProt predicts a signal peptide or a membrane-spanning region. PROTAC: ubiquitination databases record sites on it.
Gene: Protein-coding gene on chromosome 17 (55,718,739 to 55,732,121, reverse strand). Ensembl gene ENSG00000166292.
Subcellular location: Cell membrane; Membrane; Perikaryon; Cytoplasm, perinuclear region; Endoplasmic reticulum
Subcellular location (Human Protein Atlas): Nucleoplasm
Gene Ontology:
Molecular function: protein binding
Biological process: BMP signaling pathway; cellular response to BMP stimulus; positive regulation of endothelial cell differentiation; positive regulation of vasculogenesis; regulation of sensory perception of pain
Cellular component: endoplasmic reticulum; perikaryon; perinuclear region of cytoplasm; plasma membrane; membrane
Genetic constraint (gnomAD): Loss-of-function variants: 0 observed, 6.52 expected, observed/expected ratio (o/e) 0, 90% interval 0 to 0.46. That is too few expected variants to judge how well the gene tolerates losing a copy. Missense variants: 137 observed, 177.06 expected, observed/expected ratio (o/e) 0.77, 90% interval 0.67 to 0.89. Synonymous variants: 61 observed, 70.66 expected, observed/expected ratio (o/e) 0.86, 90% interval 0.7 to 1.07.
Homologues: Orthologues: chimpanzee TMEM100 (100% identical), macaque TMEM100 (99% identical), rabbit TMEM100 (92% identical), dog TMEM100 (90% identical), pig TMEM100 (87% identical), rat Tmem100 (86% identical), mouse Tmem100 (85% identical), guinea pig TMEM100 (83% identical), tropical clawed frog tmem100 (72% identical). Paralogues in human: PIRT (19% identical).
Diseases named in the same sentence as TMEM100 in open-access papers:
TMEM100 is named in the same sentence as 36 diseases in open-access papers, as found by Europe PMC text mining. Sharing a sentence is not in itself a finding about the gene and the disease. The quoted sentences say what the papers report.
lung carcinoma (7 papers, 2015 to 2026). "The molecular mechanisms underlying TMEM52B loss in lung cancer remain largely unexplored, whereas TMEM100 has been extensively investigated in pulmonary tumors." (PMID 41596760, 2026). "The development of peptides or antibodies that selectively target TMEM100 may also offer diagnostic and therapeutic opportunities for the early detection and treatment of lung cancer given TMEM100’s role as a tumor suppressor in specific cells." (PMID 36979916, 2023). "Approximately 50 TMEMs have been found to be deregulated and have been studied in lung cancer; some predominantly act as tumor suppressors (e.g., TMEM100 and TMEM196), while others function as oncogenes (e.g., TMEM14A and TMEM158)." (PMID 41596760, 2026). "In functional studies in vitro, the authors found that TMEM100 inhibited colony formation and tumor growth when overexpressed in lung cancer cell lines." (PMID 36979916, 2023). "It has been reported that TMEM100 is expressed in blood vessels, notochords, and other tissues and is related to kidney development, angiogenesis, and lung cancer metastasis." (PMID 37469758, 2023). "TMEM100 exhibited a clear inhibition of metastasis and proliferation in lung cancer, prostate cancer (PC), hepatocellular carcinoma (HCC) and gastric cancer (GC), and is correlated with the prognostic outcomes of above malignancies." (PMID 35928881, 2022). "They found TMEM100 was downregulated in lung cancer and inhibited the proliferation of lung cancer cells." (PMID 25978032, 2015). "Additionally, TMEM100 is downregulated in various kinds of cancers including lung cancer and other lung diseases, and contributes to disease progression." (PMID 36979916, 2023). "Therefore, there is a possibility that TMEM100 could serve as a biomarker for the early detection of various lung diseases, including lung cancer and PAH." (PMID 36979916, 2023). "In cases where there is cell death due to the progression of lung diseases such as lung cancer or PAH, TMEM100 could potentially be released into the circulation." (PMID 36979916, 2023). "TMEM100 was also reported to be downregulated in NSCLC and lung cancer cell lines." (PMID 36067196, 2022). "However, TMEM100 inhibited the EMT process of HCC, lung cancer, PC and CRC." (PMID 35928881, 2022).
gastric cancer (6 papers, 2021 to 2025). A primary or metastatic malignant neoplasm involving the stomach. "Recent studies also showed that TMEM100 was identified as a diagnostic gene for gastric cancer via re-analyzing the existing gastric cancer datasets." (PMID 36979916, 2023). "A recent study has indicated that upregulation of TMEM100 activity in vivo inhibited lung metastasis of gastric cancer cells, suggesting that TMEM100 may be linked with tumor invasion and metastasis." (PMID 34422038, 2021). "The expression of TMEM100 effectively predicts overall survival, first progression and post-progression survival in gastric cancer patients." (PMID 36979916, 2023). "For example, the correlation between hsa-miR-372 and TMEM100 plays an important role in the oncogenesis and progression of several types of cancer, including bladder cancer, colorectal cancer, and gastric cancer." (PMID 36712850, 2022). "Meanwhile, the most downregulated gene TMEM100 is minimally expressed in non-small cell lung cancer and enhances the sensitivity to chemotherapy in gastric cancer, which is a finding highly similar to ours." (PMID 34540825, 2021). "In addition to its role in GBM, TMEM100 serves as a prognostic marker in esophageal cancer, LUAD, and gastric cancer, where it is closely linked to immune cell infiltration 71-73." (PMID 40302809, 2025). "TMEM100 is noticeably downregulated in gastric cancer (GC) tissue." (PMID 34422038, 2021). "Moreover, the overexpression of TMEM100 sensitized gastric cancer cells to chemotherapeutic drugs." (PMID 36979916, 2023). "Indeed, TMEM100 expression was significantly downregulated in gastric cancer patients." (PMID 36979916, 2023). "TMEM100 expression is downregulated in multiple cancer tissue and cell lines, including lung adenocarcinoma (LUAD) and lung squamous cell carcinoma (LUSC), colorectal cancer, gastric cancer, and PCa." (PMID 36979916, 2023).
colorectal cancer (5 papers, 2021 to 2025). A primary or metastatic malignant neoplasm that affects the colon or rectum. "However, the biological role of TMEM100 in human cancers, particularly colorectal cancer (CRC), is unclear." (PMID 35928881, 2022). "The overexpression of TMEM100 shortens the half-life of hypoxia-inducible factor-1α (HIF-1α) via ubiquitination and the proteasome pathway and inhibits colorectal cancer cells’ migration and angiogenesis potential." (PMID 36979916, 2023).
hepatocellular carcinoma (5 papers, 2015 to 2022). A malignant tumor that arises from hepatocytes. "Interestingly, TMEM100, a core enrichment gene upregulated in the M0 subgroup, is a tumor suppressor gene in non-small cell lung carcinoma as well as in hepatocellular carcinoma." (PMID 34476575, 2021). "Then, to further verify this hypothesis, we analyzed the expression of TMEM100 in ANLTs, well differentiated hepatocellular carcinoma and poorly differentiated hepatocellular carcinoma by immunohistochemistry." (PMID 25978032, 2015). "We found that TMEM100 was decreased in hepatocellular carcinoma (HCC) tissues and in highly metastatic cell lines." (PMID 25978032, 2015). "Both of the expression of TMEM100 and Ki-67 were strong positive in ANLTs, moderate positive in well differentiated hepatocellular carcinoma and week positive or negative in poorly differentiated hepatocellular carcinoma." (PMID 25978032, 2015).
lung adenocarcinoma (4 papers, 2022 to 2023). A carcinoma that arises from the lung and is characterized by the presence of malignant glandular epithelial cells. "Hsa_circ_0000567 can act as a sponge for miR-421, which increases cell migration and invasion by directly binding to the 3′-UTR of TMEM100 mRNA in lung adenocarcinoma." (PMID 35884948, 2022). "Downregulation of circ_0000567 accelerates the development of lung adenocarcinoma via the hsa_circ_0000567/miR-421/TMEM100 axis." (PMID 35884948, 2022). "Furthermore, from gene expression analysis on the samples, the authors found that TMEM100 transcripts were reduced in less-differentiated cells, such as invasive lung adenocarcinomas, suggesting the tumor-suppressor capabilities of TMEM100." (PMID 36979916, 2023).
prostate carcinoma (4 papers, 2022 to 2025). A carcinoma that arises from epithelial cells of the prostate gland. "Similarly, TMEM100 was shown to decrease in the prostate cancer patients, and low TMEM100 expression was associated with advanced tumor stage and metastasis." (PMID 36979916, 2023). "However, whether the expression of TMEM100 is associated with the development and prognosis of prostate cancer (PCa) remains elusive." (PMID 35358005, 2022). "The overexpression of TMEM100 suppressed prostate cancer cell progression by inhibiting the FAK/PI3K/AKT signaling pathway." (PMID 36979916, 2023). "In another study, researchers constructed a miRNA-mRNA regulatory network containing miR-106b-5p to identify genes such as TMEM100, FRMD6, NBL1, and STARD4 for the diagnosis and prognosis of prostate cancer patients." (PMID 38818039, 2024).
glioma (3 papers, 2019 to 2025). A benign or malignant brain and spinal cord tumor that arises from glial cells (astrocytes, oligodendrocytes, ependymal cells). "Moreover, expression levels of PDPN were significantly correlated with increasing glioma grade, whereas TMEM100 showed the opposite pattern, suggesting that both of these markers are associated with prognosis, even when low-grade glioma samples were included." (PMID 31332251, 2019). "Other fc3 genes in the curated set, FERMT1, TMEM100, DYNLT3, EPHB1, IGFBP2, NNMT, and SH3GL2 all show direct evidence to a relationship with glioma biology and patient prognosis." (PMID 39941811, 2025). "The role of NEGR1 and TMEM100 in glioma has not yet been reported." (PMID 36358948, 2022). "From the transcriptome data analysis results in the public database, it was found that CDK4, PBK, ANGPTL2, TMEM100, and MEX3A were significantly up-regulated in the glioma samples compared with the normal samples, whereas NEGR1 and SLC2A3 were down-regulated in the glioma samples at the mRNA level." (PMID 36358948, 2022).
Cirrhosis (2 papers, 2015 to 2018). A chronic disorder of the liver in which liver tissue becomes scarred and is partially replaced by regenerative nodules and fibrotic tissue resulting in loss of liver function. "Low levels of TMEM100 were associated with cirrhosis, tumor size, Tumor nodule number, TNM stage, BCLC stage, Edmondson-Steiner Stage and vein invasion." (PMID 25978032, 2015). "TMEM100 expression was significantly associated with cirrhosis (p = 0.03), tumor size (p < 0.001), Tumor nodule number (p < 0.001), TNM stage (p < 0.001), BCLC stage (p < 0.001), Edmondson-Steiner Stage (p = 0.002) and vein invasion (p < 0.001), respectively." (PMID 25978032, 2015). "On univariate survival analysis, cirrhosis (p = 0.012, p = 0.038), tumor nodule number (p = 0.019, p = 0.036), vein invasion (p = 0.024, p = 0.013) and TMEM100 expression (p = 0.008, p = 0.009) reached significance for overall survival (OS) and Disease-free survival (DFS), respectively." (PMID 25978032, 2015).
kidney failure (2 papers, 2015 to 2023). An acute or chronic condition that is characterized by the inability of the kidneys to adequately filter the blood. "Given these diverse roles, it is essential to further investigate the specific roles that TMEM100 plays in the development of pathological conditions, such as PAH and kidney failure, as well as the progression of various cancers." (PMID 36979916, 2023).
peripheral nerve injuries (2 papers, 2019 to 2023). "However, the mechanism of pain regulation and the expression of TMEM100 following various peripheral nerve injuries are unclear." (PMID 37469758, 2023). "Pain induces alteration of Tmem100 expression in a pathology-dependent manner, upregulated after CFA-inflammatory pain but dramatically downregulated in the injured DRGs after peripheral nerve injury." (PMID 30801043, 2019). "We further characterized Tmem100 expression in the CFA-inflammatory pain model and in peripheral nerve injury–induced neuropathic pain in rats." (PMID 30801043, 2019). "Our data indicate that painful conditions are accompanied by divergent alterations of Tmem100 expression in a pathology-dependent manner, with upregulation after CFA-inflammatory pain, as in a previous study, but dramatic downregulation in the injured DRGs after peripheral nerve injury." (PMID 30801043, 2019).
aspergillosis (1 paper, 2022). Aspergillosis is an infection, growth, or allergic response caused by the Aspergillus fungus. "The fact that all of the miRNAs targeting TMEM100 have shown significant changes in gene expression in HO patients with aspergillosis also suggests its involvement in both potentially oncogenic and infection-related biological pathways." (PMID 35504997, 2022).
Dry skin (1 paper, 2022). Skin characterized by the lack of natural or normal moisture. "First, we found that spontaneous itch behaviors, indicated by biting the AEW-treated hind leg, were dramatically decreased in the KD group compared with that in the scramble group, suggesting the possible treatment effect of dry skin-induced itch through modulation of TMEM100." (PMID 36514220, 2022). "In Renji Hospital, this technique has been routinely used to treat chronic pain patients, so hopefully we can develop a new valid itch alleviation strategy for dry skin-induced itch-tortured patients after further evaluation of the effectiveness and safety of TMEM100 interference." (PMID 36514220, 2022). "Furthermore, decreasing TMEM100 protein expression could be an effective curative strategy for alleviating dry skin-induced chronic itching." (PMID 36514220, 2022). "Our results strongly suggest that TMEM100 protein in DRG is the main facilitating factor for dry skin-related chronic itch, and specific suppression of TMEM100 in DRG could be a novel effective treatment strategy for patients who suffer from dry skin-induced itch." (PMID 36514220, 2022). "In the present study, we mainly focused on the role of TMEM100 in the AEW itch model and the regulatory mechanism of TMEM100 in TRPV1 and TRPA1 functional changes to clarify the mechanism of the TRPV1 and TRPA1 functions modulated by TMEM100 during dry skin-induced itch." (PMID 36514220, 2022).
esophageal squamous cell carcinoma (1 paper, 2025). Esophageal squamous cell carcinoma (ESCC) is a type of esophageal carcinoma (EC) that can affect any part of the esophagus, but is usually located in the upper or middle third. "The overexpression of TMEM100 has been shown to inhibit the proliferation, invasion, and migration of esophageal squamous cell carcinoma cells." (PMID 40302809, 2025).
hereditary hemorrhagic telangiectasia (1 paper, 2015). A disorder of angiogenesis leading to arteriovenous dilatations: cutaneo-mucosal hemorrhagic telangiectasias and visceral shunting. "TMEM100 transcripts associated with transcripts for activin receptor-like kinase I (ALK1), the gene mutated in hereditary hemorrhagic telangiectasia." (PMID 25978032, 2015).
itch (1 paper, 2022). "To further investigate the relationship between TMEM100 and TRPA1 and the possible treatment effect of AEW itch through modulation of TMEM100, we synthesized adeno-associated virus (AAV) vectors containingTmem100-shRNA." (PMID 36514220, 2022). "These gene coexpression results show thatTmem100-,Trpa1- andMrgpra3-positive neurons should be the main neuron population for AEW itch and that TMEM100 facilitates TRPA1 function and AEW itch sensation mainly in this population of DRG neurons." (PMID 36514220, 2022). "Combined with increased c-Fos expression in TMEM100+ neurons and TMEM100 expression in the AEW model, the TMEM100 protein could be a pivotal target for AEW itch alleviation through direct effects on itch-related TRPA1 function." (PMID 36514220, 2022). "In the present study, we found that the TMEM100 was upregulated in DRG neurons and enhanced neuron excitability and itch sensitivity in an AEW itch model." (PMID 36514220, 2022). "In the AEW itch model, the itch-facilitating effect of TMEM100 is achieved mainly through the modulation of TRPA1 but not TRPV1." (PMID 36514220, 2022).
metastatic tumors (1 paper, 2022). "Histology showed that the abundance of metastatic tumors in lungs of TMEM100 overexpression group were low, relative to control group." (PMID 35928881, 2022).
migraine (1 paper, 2023). "Future studies are needed to investigate whether TMEM100 is also involved in modulating other types of trigeminal pain, such as dental pain, migraine, and trigeminal neuralgia." (PMID 37033371, 2023). "In addition, based on the data showing that 95 and 74% of TMEM100-positive sensory neurons express CGRP in mice and rats, respectively, and in view of CGRP’s crucial role in migraine, it would be interesting to investigate whether TMEM100 contributes to migraine via regulating CGRP levels." (PMID 37033371, 2023).
pulmonary diseases (1 paper, 2023). "Future studies should focus on identifying the molecular relationships between TMEM100 and its upstream and downstream regulators and how these relationships affect vascular development and the pathogenesis of pulmonary diseases." (PMID 36979916, 2023). "This review summarizes the current knowledge of TMEM100, including its expression pattern, function, molecular signaling, and clinical implications, which could be valuable in the development of novel therapies for the treatment of cardiovascular and pulmonary diseases." (PMID 36979916, 2023).
pulmonary hypertension (1 paper, 2023). Increased pressure within the pulmonary circulation due to lung or heart disorder. "Studies have found that TMEM100 expression is downregulated in the lungs during inflammatory lung injury and pulmonary hypertension, and that Tmem100 deficiency impairs lung vascular regeneration after injury." (PMID 36979916, 2023).
Wilms tumor (1 paper, 2023). An embryonal neoplasm characterized by the presence of epithelial, mesenchymal, and blastema components. "Genes identified as targets of wild-type SIX1 in both Wilms tumor and hFK but not of SIX1-Q177R include established NPC-enriched genes FOXC1 and TMEM100, both of which were also found to be upregulated in SIX1/2-Q177R tumors." (PMID 37815464, 2023).